EGFR (epidermal growth factor receptor)
Diseases named in the same sentence as EGFR in open-access papers (continued):
Sharing a sentence is not in itself a finding about the gene and the disease.
lung cancer (continued). "It has been described that Cytohesin overexpression enhances epidermal growth factor receptor (EGFR) signaling in human cancers including lung cancer and colorectal cancer." (PMID 26269779, 2015). "EGFR genotyping of the lung cancer cell lines Ma1, 11–18 and A549 had been performed by sequence analysis in our previous study, and were revealed as delE746-A750, L858R and wild-type, respectively." (PMID 25591975, 2015). "Similar results were obtained in other lung cancer cell lines, e.g., the H3255 cell line bearing an L858R EGFR mutant and the H1975 cell line containing an L858R/T790M EGFR mutant." (PMID 25955608, 2015). "The involvement of miRNAs in the EGFR signaling pathway of lung cancer development and target therapy has recently gained increasing attentions." (PMID 26273639, 2015). "To prove that FEEST can be used to generate mice that are transgenic for other genes, we set out to generate transgenic mice for EGFR L858R, one of the mutant EGFRs that is most frequently found in lung cancer patients." (PMID 26573149, 2015). "Despite the efficacy of EGFR tyrosine kinase inhibitors (TKIs), patients with EGFR mutant lung cancers eventually develop resistance to EGFR TKIs." (PMID 26322518, 2015). "Patients with EGFR-mutant lung cancers expressing high levels of Bim showed longer progression-free survival (PFS) than those with tumors expressing low levels of Bim." (PMID 26405162, 2015). "This study presents indications that EGFR and Notch signalling pathways crosstalk in human lung cancer cell lines." (PMID 26497899, 2015). "Treatment with EGFR tyrosine kinase inhibitors (TKIs) is the standard of care for molecularly selected EGFR-mutant patients, while its role in unselected lung cancer patients is nowadays controversial." (PMID 25810955, 2015). "In our study, UCA1 expression was significantly increased in lung cancer cells and patients with acquired resistance to EGFR-TKIs." (PMID 26160838, 2015). "We found that HDN-1 upregulated the phosphorylation of EGFR at Tyr1045 in the three types of lung cancer cells in dosage- and time-dependent manners." (PMID 25742791, 2015). "Examples are cetuximab or panitumumab approved for several indications including colorectal or head and neck tumors, or EGFR-directed small kinase inhibitors in lung cancer." (PMID 26418718, 2015). "We therefore examined the collective contribution of EGFR, HER2 and HER3 in the molecular mechanism underlying the pathogenesis of KRAS mutant lung cancer." (PMID 25992771, 2015). "EGFR mutations and ALK gene fusions are the key molecular treatment predictive alterations for targeted therapy in lung cancer today." (PMID 26124082, 2015). "EGFR inhibitors, angiogenesis inhibitors, and monoclonal antibodies have been analyzed in clinic trials with promising results in some subtypes of lung cancer." (PMID 26056041, 2015). "CXCL1 functions through CXCR2, a G protein-coupled receptor that transactivates EGFR in ovarian and lung cancers." (PMID 26462152, 2015). "EGFR is highly expressed in many epithelial cancers, including lung cancer, colorectal cancer, head and neck cancer, and HCC." (PMID 26436086, 2015). "Non-small cell lung carcinoma (NSCLC) represents approximately 80% of lung cancer cases, and over 60% of these tumors express the epidermal growth factor receptor (EGFR)." (PMID 25853010, 2015). "This review will provide an overview of the EGFR pathway and options for its treatment of lung cancer." (PMID 25810955, 2015). "Furthermore, CQ appears to be therapeutically useful for both gefitinib-sensitive and -resistant NSCLC, suggesting that CQ and its analogs may be a promising cancer therapy for lung cancer patients with EGFR mutation who develop an acquired resistance after receiving gefitinib treatment." (PMID 25807554, 2015). "Recent studies have reported that germline mutations in EGFR and HER2 genes can predispose the development of lung cancer." (PMID 26075181, 2015).
lung cancer (continued). "We recently showed rapid induction of FGFR2 and FGFR3 expression in lung cancer cell lines following treatment with EGFR-specific TKIs." (PMID 25946135, 2015). "In several preclinical studies based on lung cancer cell lines and xenografts, EGFR expression was down regulated in response to estrogen and up-regulated in response to ER antagonists (i.e., fulvestrant or tamoxifen) in NSCLC cell lines." (PMID 26096604, 2015). "In China, few innovative targeted anti-cancer agents for lung cancer have been successfully developed, except for icotinib, which is an EGFR TKI approved for advanced NSCLC by the China FDA (CFDA)." (PMID 26162603, 2015). "EGFR signaling has been shown to enhance HGF-induced c-MET phosphorylation levels in lung cancer cell lines." (PMID 26260789, 2015). "Using ELISA, we found that metformin significantly decreased TGF-β levels in EGFR-TKI-treated lung cancer cells." (PMID 26497205, 2015). "Afatinib, a clinically available 2nd generation EGFR-TKI, is potent against EGFR mutated lung cancer cells in vitro and in vivo." (PMID 26515464, 2015). "Treatment with EGFR kinase inhibitors improves progression-free survival of patients with EGFR-mutant lung cancer." (PMID 26540572, 2015). "While EGFR emerged as the most interesting candidate, other genes with intriguing connections to lung cancer biology, including HMGA2, BCL2, and others, will be the focus of future studies." (PMID 26556242, 2015). "Nevertheless, the biochemical basis of the EGFR and Notch interaction has been unclear, and likewise its role in lung cancer biology." (PMID 26474174, 2015). "Through quantitative measurement of the drug-resistant and sensitive lung cancer cells, this motif-targeting approach suggested potential drug-targeting proteins in the EGFR- and CK2-centred kinase–substrate network." (PMID 25814448, 2015). "The design of new drugs to treat lung cancer patients who become resistant to EGFR-directed therapy due to the emergence of the T790M secondary mutations represents a perfect example of the importance of research efforts in the field of secondary resistance." (PMID 26427052, 2015). "Many studies have shown that gene copy variation directly affected gene expression; for example, the DNA copy number of HER-2 and EGFR mediated the overexpression of these genes in breast and lung cancer, respectively." (PMID 26467212, 2015). "For screening of EGFR signaling inhibitors for lung cancer therapy, we downloaded the x-ray crystal structure of EGFR kinase domain from the Protein Data Bank, and Autodock4.2 software package was employed to perform the molecular docking modeling assay." (PMID 25730907, 2015). "To validate the analysis of lncRNAs profiles, we assessed the mRNA expression of UCA1 by RT-PCR in lung cancer cell lines and patients with EGFR-mutant NSCLC." (PMID 26160838, 2015). "Treatment of EGFR-mutant lung cancer with erlotinib results indramatic tumor regression but it is invariably followed by drug resistance." (PMID 25686219, 2015). "In another preclinical study, the sequence-dependent synergism between paclitaxel and gefitinib was demonstrated in human lung cancer cell lines with both wild-type and mutant EGFR genes." (PMID 26493267, 2015). "In our study, an EGFR wild-type lung cancer cell line, A549, was used to screen Src kinase inhibitors." (PMID 25955608, 2015). "These include BRAF mutation analysis for melanoma, EGFR and ALK testing for lung cancer and RAS testing for colorectal cancer." (PMID 26101870, 2015). "In contrast, stem cells were highly resistant to the EGFR inhibitor erlotinib, a widely used drug for lung cancer, and the ERK inhibitor PD98059, which is active against a variety of cancer cell lines (dashed lines)." (PMID 27867772, 2015). "The resistance to the EGFR-TKIs gefitinib and erlotinib ultimately develops in all patients with metastatic EGFR mutant lung cancer." (PMID 26622796, 2015).
lung cancer (continued). "The evidence of miRNA participating in the EGFR/c-MET network in lung cancer thus provides a new clue to overcoming EGFR-TKI resistance in lung cancer." (PMID 26273639, 2015). "Taken alltogether, these results indicate that suppression of EGFR signaling in mutantEGFR-addicted lung cancer cells is highly specific in triggering transcriptionalinduction of SOX2." (PMID 25686219, 2015). "Intriguingly, several tumor-suppressive miRNAs exhibited an ability to enhance the cytotoxicity of EGFR-TKI to lung cancer cells, such as miR-126, miR-145, and miR-146a." (PMID 26273639, 2015). "Epidermal growth factor receptor (EGFR) and KRAS must be detected mutation status before patients of lung cancer use targeted drugs." (PMID 25936883, 2015). "Our study on a series of EGFR mutant advanced lung cancers receiving 1st line Gefitinib suggests that the presence of ACM significantly decreases the expected benefit of TKIs." (PMID 25904052, 2015). "We developed a scoring system in EC based upon established systems for EGFR fluorescence in-situ hybridisation (FISH) in lung cancer, and applied this in a series of 160 UK patients with advanced EC." (PMID 26478746, 2015). "For the treatment of EGFR-mutant lung cancer, EGFR TKIs are recommended as first-line regimens because of their superior efficacy to platinum doublet regimens in terms of progression-free survival." (PMID 26555338, 2015). "Recently, molecular targeting therapies against epidermal growth factor receptor (EGFR) have gained increasing recognition in the treatment of lung cancer." (PMID 25886900, 2015). "Here we present a strategy for improving therapeutic efficacy in a xenograft model of EGFR-mutant lung cancer by intermittent high-dose scheduling of erlotinib." (PMID 26540572, 2015). "USP18 overexpression is associated with augmented oncogene or growth factor receptor expression such as the epidermal growth factor receptor (EGFR) and tumor-promoting effects in acute promyelocytic leukemia, kidney and lung cancer." (PMID 26555296, 2015). "Among 1310 lung cancer patients diagnosed between January 2011 and October 2013, 486 patients with advanced NSCLC were screened for EGFR mutations." (PMID 26313661, 2015). "Of 1310 lung cancer patients diagnosed between January 2011 and October 2013, 253 patients receiving first-line EGFR-TKIs for EGFR-mutant NSCLC were included." (PMID 26313661, 2015). "Mutations in EGFR and ALK gene fusions represent current molecular treatment predictive alterations for targeted therapy in lung cancer, but rarely appear in LC or LCNEC tumors with only a few reported cases in the literature." (PMID 26124082, 2015). "Novel therapies include the targeting of biomarkers, such as EGFR, that are commonly overexpressed in lung cancers." (PMID 26517520, 2015). "To explore the translational application of SH2-PLA, we analyzed binding of Grb2 SH2 to EGFR in lung cancer patient tissues." (PMID 26112401, 2015). "Although the contribution of EGFR signalling in lung cancer development is well established, the importance of Notch pathway in lung cancer is under investigation." (PMID 26497899, 2015). "Specific droplet digital PCR assays were used for serial plasma genotyping of EGFR-mutant lung cancer in patients being treated with erlotinib." (PMID 26101870, 2015). "In selecting lung cancer patients with solitary gastric metastasis for specific targeted therapies by EGFR analysis, special attention should be given to the metastatic lesions rather than their corresponding primary tumors." (PMID 25663915, 2015). "The in vitro tests conducted on EGFR overexpressing A549 and H226 lung cancer cells revealed that the nanoparticles were internalized by the cells via a receptor-mediated endocytosis." (PMID 26605001, 2015). "Axl has been shown to increase EGFR-conferred chemoresistance in lung cancer, while it diversifies EGFR signalling and increased resistance to targeted therapy in triple negative breast cancer." (PMID 25980499, 2015).
lung cancer (continued). "In contrast to lung cancers with EGFR exon 19 deletions, those with exon 20 insertions are generally resistant to the currently available reversible EGFR inhibitors gefitinib and erlotinib." (PMID 26697520, 2015). "Human HCC827 lung cancer cell line was tested with epidermal growth factor receptor (EGFR) targeted hybrid plasmonic core/shell iron oxide gold nanoparticles (225 NP)." (PMID 26437397, 2015). "One of important findings of this study was that over-expression of UCA1 in lung cancer cells and patients with acquired resistance to EGFR-TKIs." (PMID 26160838, 2015). "Several reports have analysed tumour heterogeneity in acquired resistance mechanisms to EGFR-TKI in lung cancers." (PMID 26400668, 2015). "First, we used different lung cancer cell line and we just focused on EGFR mutant lung cancer cells." (PMID 26096604, 2015). "The cross-talk between ERα and EGFR (Epidermal growth factor receptor) pathway has been reported in lung cancer, esophagus cancer and neck squamous cell carcinoma." (PMID 26122040, 2015). "Crucial targets of Hsp90-active drugs vary in different cell types, and Hsp90 is permissive for the development of mutant EGFR-dependent lung cancers, these kinase domain mutants are degraded by Hsp90 inhibitors." (PMID 25742791, 2015). "The expression of PD-L1 in lung cancer is detected in 25–50% of NSCLC cases, depending on the assays used to detect its protein or mRNA, and is associated with the presence of EGFR mutations in NSCLC." (PMID 26134262, 2015). "Mechanistic evidence showed that miR-7 can inhibit the proliferation of lung cancer cells through regulating the expression of EGFR by binding to the 3′UTR region of EGFR mRNA." (PMID 26516313, 2015). "This indicates that combined use of YangZheng XiaoJi and HGF receptor inhibitor is an effective way to overcome resistance to anti-EGFR therapy in lung cancer and should be explored in clinical settings." (PMID 26310485, 2015). "Virtually all EGFR-mutant lung cancer cell lines established from patients who havenot been treated with erlotinib are highly sensitive to this drug, although a fewcells lines appear to be intrinsically resistant." (PMID 25686219, 2015). "Advanced lung cancers with epidermal growth factor receptor (EGFR) exon 19 deletions (Ex19s) and EGFR exon 21 L858R point mutations (Ex21s) exhibit different clinical behavior." (PMID 26496308, 2015). "It has been reported that lung cancer- derived EGFR active- site mutants are constitutively active and thus oncogenic, even without EGF, and that this activation is probably caused by interaction with Src." (PMID 25803810, 2015). "We also highlight the evidence supporting the use of miRNAs as biomarkers for response to anti-EGFR agents and as novel therapeutic targets to circumvent the resistance of lung cancer cells to EGFR inhibitors." (PMID 26273639, 2015). "Similar to miR-21, which was also more aberrantly expressed in EGFR-TKI-resistant lung cancer cell line PC9R relative to its parent cell PC9." (PMID 26273639, 2015). "Collectively, these results indicate that the lung cancer cells harbored the EGFR-L858R mutant promotes the formation of MPE in vivo." (PMID 26338423, 2015). "The discovery of targeted therapy has led to a new era of individualized treatment in lung cancer; epidermal growth factor receptor (EGFR) tyrosine kinase inhibitors (TKIs) have been a new paradigm of lung cancer treatment." (PMID 25873045, 2015). "With the use of this two-tier strategy, we reliably determined the frequency of EGFR mutations and EGFR, MET and ERBB2 amplifications in over 200 lung cancer samples." (PMID 25719557, 2015). "In the present study, we analyzed the mitochondria proteomics of lung cancer cell lines with different invasion abilities and found that EGFR is highly expressed in the mitochondria of highly invasive non-small-cell lung cancer (NSCLC) cells." (PMID 26497368, 2015).
lung cancer (continued). "Further we showed that SH2-PLA unambiguously detected a relatively low level of EGFR phosphorylation in lung cancer tissues using far less cell lysates than typically available from a core needle biopsy (~105 cells or 100 μg)." (PMID 26112401, 2015). "In the past decade, lung cancer treatments have generally focused on targeted therapies such as epidermal growth factor receptor (EGFR) tyrosine kinase inhibitors and anaplastic lymphoma kinase (ALK) fusion protein inhibitors." (PMID 29546098, 2015). "In a type of lung cancer called adenocarcinoma, the KRAS gene is mutated in about one-third of tumors and the EGFR gene is mutated in about 15%." (PMID 26047463, 2015). "Proof-of-concept experiments using CK2-, MAPK- and EGFR-targeting assays in lung cancer cells demonstrate the advantage of kinase-targeted complexity reduction, resulting in deeper phosphoproteome quantification." (PMID 25814448, 2015). "Given the fact that only small portion of patients with lung cancer benefit from a treatment of EGFR-TKIs, the benefits of these agents to patients are ultimately limited by the emergence of drug resistance." (PMID 26273639, 2015). "Our study findings thus show that AUY922 is a promising therapeutic option for MET- and AXL-mediated resistance to EGFR-TKI in lung cancer." (PMID 25780909, 2015). "It is observed that in human lung cancer cell line NCI-H292 cells, inhibition of the Notch pathway decreased both the Notch and EGFR/ERK pathways, associated with the reduction of proliferative cells." (PMID 25996086, 2015). "In lung cancer cells, the EGFR-PGRMC1 complex drives invasion, at least in part, by activating matrix metalloproteinases." (PMID 27867772, 2015). "Further characterization of these proteins (mainly lung-enriched surface antigens and proteins related to epidermal growth factor receptor [EGFR] signaling) indicated their potential in lung cancer diagnosis." (PMID 25883534, 2015). "The cell lines established from biopsies of resistant EGFR mutant lung cancers were assessed for RB expression." (PMID 25758528, 2015). "Both EGFR and c-MET are RTKs that have been implicated in tumor progression as regulators of miRNA cluster 23a/27a~24-2 in lung cancer, in which miR-27a can regulate both c-MET and EGFR." (PMID 26273639, 2015). "In randomized studies, the median overall survival of patients with EGFR mutant lung cancer receiving first-line EGFR TKIs is 19 to 36 months, while median progression-free survival is about a year." (PMID 26517520, 2015). "Clinically relevant driver mutations, e.g., in EGFR, KRAS, and ELM4-ALK fusion, were present in 40% of the lung cancer patients." (PMID 26496203, 2015). "For example, CQ has been shown to overcome primary resistance of epidermal growth factor receptor (EGFR) tyrosine kinase inhibitors (TKIs) in A549 lung cancer cells and trastuzumab in HER-2 positive breast cancer." (PMID 25807554, 2015). "EGFR signalling was shown to be involved in PD-L1 expression in non-small cell lung cancer and pharmacological blockade using tyrosine kinase inhibitors of EGFR showed significant reduction in mouse lung cancer model systems." (PMID 25844720, 2015). "A study of 93 patients with EGFR-mutant lung cancer and acquired resistance to EGFR TKIs compared T790M status in terms of postprogression survival and characteristics of disease progression." (PMID 25699082, 2015). "Acquired resistance to EGFR and c-Met TKIs is a common occurrence in patients which limits the overall efficacy of current lung cancer therapies." (PMID 26301867, 2015). "Twelve differentially expressed miRNAs were selected for the analysis because of their known roles in tumorigenesis of lung cancer, resistance to drugs, and regulation of EGFR pathway." (PMID 26563758, 2015). "This study focuses on elucidating key signaling proteins in alternative signaling pathways which result in EGFR/c-Met TKI resistance in lung cancer cell lines which have wild type EGFR or EGFR with T790M mutation." (PMID 26301867, 2015).